SMARCA4 (SWI/SNF related BAF chromatin remodeling complex subunit ATPase 4)
Diseases named in the same sentence as SMARCA4 in open-access papers (continued):
Sharing a sentence is not in itself a finding about the gene and the disease.
tumor (continued). "The solid predominant tumors (patients Ch–j), all harboring truncating SMARCA4 variants, had solid (patients Ch–j) and acinar (patient Ci) tumor areas that were BRG1 negative." (PMID 35964518, 2022). "The results indicated a somatic SWI/SNF-related, matrix-associated, actin-dependent regulator of chromatin, subfamily A, member 4 (SMARCA4) mutation, microsatellite stability, and a tumor mutation burden of 1.0 muts/Mb without any germline mutations." (PMID 35903699, 2022). "According to these findings, the tumour was diagnosed as an SMARCA4‐UT." (PMID 35822082, 2022). "However, the functional role of SMARCA4 seems to be rather complicated in tumorigenesis, as both tumor-suppressive and oncogenic roles have been revealed during different stages of pancreatic tumorigenesis." (PMID 36361605, 2022). "Furthermore, tumor suppressor genes with a mutational frequency of >10% in cell lines involved SMAD4, SMARCA4, ARID1A, ARID2, and RBM10." (PMID 36013219, 2022). "High tumor mutational burden (TMB, 23.93/Mb) and mutations in SMARCA4 were detected." (PMID 36452500, 2022). "Mutations in ARID1A (p = 0.0205), ARID2 (p = 0.0207), BRAF (p = 0.023) SMARCA4 (p = 0.015), TERT (p = 0.0041), and IDH1 (p = 0.0041) were significantly exclusive to BM while the same variants remained undetected in the corresponding extracranial tumor tissues." (PMID 33578810, 2021). "Thus, discrepancies abound regarding the functions of SMARCA4 with respect to tumor initiation and progression in gut." (PMID 33853662, 2021). "Other studies, however, have reported a tumor-promoting role of SMARCA4." (PMID 33853662, 2021). "Despite the genetic inactivation of SMARCA4, a core component of the SWI/SNF-complex commonly found in cancer, there are no therapies that effectively target SMARCA4-deficient tumours." (PMID 34262032, 2021). "Recent studies reported that the absence of SMARCA2 is equally necessary for the survival of SMARCA4-deficient tumor cells." (PMID 34440689, 2021). "Interestingly, SMARCA4 expression correlated with tumor size, although differences in tumor grade, TNM stage, or lymph node metastasis were not significant." (PMID 33853662, 2021). "We confirmed the presence of biallelic inactivating mutations at SMARCA4 and the lack of protein in the two patients’ tumour cells and PDOXs." (PMID 34262032, 2021). "SMARCA4 expression in tumor samples correlates with poor overall survival in several cancers." (PMID 34675941, 2021). "Besides MRTs, a role of SMARCA4 has been described for a variety of tumor entities including non-small cell lung cancer or thoracic sarcomas." (PMID 33331994, 2021). "Individuals with CSS carrying SMARCB1 or SMARCA4 mutations seem to show no predisposition to develop RTs or other forms of tumor." (PMID 33692948, 2021). "In general, SMARCA4 has been hypothesized as a tumor suppressor gene in primary lung tumors and it is required in growth arrest and cell senescence, by regulating gene expression; hence, it is a critical entity for cancer progression." (PMID 34440689, 2021). "Given that suppressed IP3R3-mediated Ca2+ flux and apoptosis has been linked to other major tumor suppressors PTEN, BAP1, and PML, in driving tumorigenesis, our above analyses suggest that this may also play a role in SMARCA4/2-deficient cancers." (PMID 34518526, 2021). "Demonstration of this mutation and/or loss of immunohistochemical staining with SMARCA4 (BRG1) may, in the correct morphological context, be crucial in the diagnosis of this highly aggressive neoplasm." (PMID 34669206, 2021). "Thus, unsurprisingly, it appears plausible that SMARCA4 can act as either an oncogene or tumor suppressor in a context- and cell type-specific manner." (PMID 33853662, 2021).
tumor (continued). "More understanding on the SMARCA4-dNSCLC shed some light on its correlation and effects on co-existence with oncogenic drivers and other tumor suppressor genes as well as possible biomarkers and immune check point inhibitors to determine optimal treatment options for metastatic tumors." (PMID 34440689, 2021). "While SMARCA4 testing has a PPV of 86% in a tertiary care referral centre for rare tumours, the projected PPV in a community hospital setting is lower; however, the NPV remains high at 99%, providing non-ovarian expert pathologist with a reliable tool to exclude SCCOHT." (PMID 31844183, 2020). "Nuclear SMARCA4 expression was retained in the different tumor components." (PMID 32507920, 2020). "In order to be clinically relevant, SMARCA4 loss of expression must provide a sensitive and specific test able to differentiate SCCOHT from tumours that are considered in the differential diagnosis; only rare tumours affecting young women and mimicking SCCOHT were included." (PMID 31844183, 2020). "Previous studies highlighted the important role of SMARCA4 as a tumor suppressor." (PMID 32629987, 2020). "SMARCA4 is more inclined to accelerate tumour development in the context of HCC and we speculate that this may be partly due to its effect in promoting immune tolerance." (PMID 32162380, 2020). "Such a confusing situation may be due to the variety of SMARCA4 functions depending on different tumour types or even the different stages and subtypes of the same tumour." (PMID 32162380, 2020). "KEAP1, DNM2, SMARCA4 were annotated as tumor suppressor genes in the Cancer Gene Census database." (PMID 32337068, 2020). "In their computational meta‐analysis, Jose et al61 demonstrated that high SMARCA4 expression was associated with aggressive tumours, while high SMARCA2 expression was related to benign differentiated tumours, suggesting that SMARCA4 and SMARCA2 play opposite roles in cancers, including HCC." (PMID 32162380, 2020). "IHC confirmed that the expression of SMARCA4 was intact in the primary tumor of VOA1066." (PMID 33052929, 2020). "Imbalances between both complexes can be due to overexpression of EZH2 in undifferentiated cancers, but most commonly occur in cancers by mutations of members of the SWI/SNF complex, such as ARID1A and SMARCA4 that together with SMARCA2 is the ATPase subunit of this tumor-suppressing complex." (PMID 33230143, 2020). "Loss of BRG1 expression and SMARCA4 loss-of-function mutations were identified in a small subset of human HCC samples, suggesting that BRG1 may also function as a tumor suppressor." (PMID 32019910, 2020). "Tumours either demonstrate complete loss (no nuclear staining) in 100% of tumour cells or significant SMARCA4 expression with a median H-score of 200 (range: 40–300)." (PMID 31844183, 2020). "Given that 5/44 SCCOHT retained some degree of SMARCA4 expression, we explored whether these SMARCA4-positive tumours may demonstrate other SWI/SNF alterations, in particular, loss of the other closely related catalytic domain, SMARCA2." (PMID 31844183, 2020). "Interestingly, SMARCA4 has been previously found to be partially required for SHH MB development, suggesting different roles of SMARCA4 depending on the MB subgroups and on the genetic alteration that are involved in tumor generation." (PMID 31996670, 2020). "Homozygous SMARCA4 mutations were highly prevalent in certain tumor types, notably non-small cell lung cancer (NSCLC), and associated with reduced survival." (PMID 33144586, 2020). "Although several mechanisms of action have been proposed above, the specific factors influencing the opposing roles of abnormal SMARCA4 among multiple tumours are still unknown." (PMID 32162380, 2020). "The tumor suppressive function of SMARCA4 is corroborated by Smarca4 knock-out studies in mice." (PMID 31406271, 2019). "In most cases, SMARCA4 acts as a tumor suppressor; however, it has context-specific oncogene roles." (PMID 31769422, 2019).
tumor (continued). "Similarly, other studies showed that SMARCA4 acts as a tumor suppressor during the oncogenic Kras-induced IPMN-PDAC formation in vivo." (PMID 31769422, 2019). "Notably, in tMSC isolated from ATRT tissue, exosome-mediated transfer of tMSC-secreted miR155 efficiently increased self-renewal and tumor growth of ATRT through suppression of SMARCA4." (PMID 31137686, 2019). "A variety of neoplasms have been discovered to have genomic alterations and loss of immunohistochemical (IHC) expression of chromatin remodelers ARID1A (BAF250A), SMARCA2 (BRM), SMARCA4 (BRG1), and SMARCB1 (INI1)." (PMID 31093468, 2018). "A variety of neoplasms have been discovered to have genomic alterations (GAs) and loss of immunohistochemical (IHC) expression of chromatin remodelers ARID1A (BAF250A), SMARCA2 (BRM), SMARCA4 (BRG1), and SMARCB1 (INI1)." (PMID 31093468, 2018). "Nonetheless, recent reports show requirement of SMARCA4 for tumor cells growth." (PMID 29391527, 2018). "Similarly, in KIRC tumors, high expression of SMARCA4 is associated with increased undifferentiated histological grade, while high levels of SMARCA2 were associated with low tumor stages and well differentiated histology." (PMID 29391527, 2018). "Tumor collections were ranked according to the SMARCA4 or SMARCA2 mRNA levels (RNA-seq data)." (PMID 29391527, 2018). "Notably, however, deletion of either of the Smarcb1 or Smarca4 tumour suppressor subunits in MEFs markedly reduced interactions between p300 and the core SWI/SNF subunit Smarcc1." (PMID 28262751, 2017). "SMARCA4 chromatin remodelling factor is mutated in 11% of Coffin–Siris syndrome (CSS) patients and in almost all small‐cell carcinoma of the ovary hypercalcaemic type (SCCOHT) tumours." (PMID 28608987, 2017). "SMARCA4-mutated RTs have not been seen in patients older than 46 months, so the development of these tumours in older carriers is unlikely." (PMID 27866340, 2017). "SMARCA4 mutations were recently reported in metastatic UM tumors, although matched primary tumor DNA was not sequenced for comparison." (PMID 28594900, 2017). "As SMARCA4 mutations overlap between SCCOHT and RTs, it is still unknown why patients develop one tumour over the other." (PMID 27866340, 2017). "Furthermore, we conclude that SMARCA4 inactivation is the main cause of SCCOHT, and that new distinct therapeutic approaches should be developed to specifically target this devastating tumor." (PMID 26646792, 2016). "Importantly, the tumor-suppressive effect of SMARCA4 knockdown could be rescued by histone deacetylase inhibitors (HDACi), achieving a level of recovery comparable to PROX1 overexpression." (PMID 41881959, 2026). "Similarly, SMARCA4 deficiency induces widespread intron retention, fostering the generation of neoantigens that enhance MHC-I presentation and elicit T cell-mediated anti-tumor immunity." (PMID 41438758, 2025). "Although the association between SMARCA4 deficiency and tumor cell undifferentiation is not fully understood, our findings suggest that SMARCA4 deficiency may serve as a useful pathologic feature for identifying U-CUP." (PMID 40866717, 2025). "In response to the presence of rhabdoid cells in the tumor, further immunohistochemical studies were conducted to investigate the SWI/SNF chromatin remodeling complex, exhibiting deficiency in SMARCA2 (BRM) while maintaining proficiency in SMARCA4 (BRG1) and SMARCB1(INII)." (PMID 40012963, 2025).
tumor (continued). "Similarly, SMARCA4-deficient MRTs, such as AT/RTs, have been noted for exhibiting high expression levels of EPHA5, indicating that the Ephrin signaling pathway may be tumor-promoting in SMARCA4-driven malignancies." (PMID 38893160, 2024). "No specific therapeutic strategies have been developed for SMARCA4-deficient neoplasms." (PMID 38374950, 2024). "However, recent research highlights that SMARCA4 assists in tumor proliferation." (PMID 38446332, 2024). "Finally, SMARCA4-UT is a rapidly metastatic aggressive tumor." (PMID 39093728, 2024). "Regarding tumor size and SMARCA4 mosaic expression, a correlation was identified (p = 0.021), indicating a statistically significant relationship where tumors displaying a mosaic expression of SMARCA4 are considerably larger in size compared to the other carcinomas studied." (PMID 39590317, 2024). "These alterations in SMARCA4‐mutant cells precipitate a heightened demand for energy, due to increased fatty acid and protein synthesis, diverging from the classical Warburg effect by shifting the tumor's energy metabolism from glycolysis to oxidative phosphorylation." (PMID 38374872, 2024). "Conversely, several of the SCLC-Y lines that we now identify to be SMARCA4-UT have previously been shown to be sensitive to CDK4/6 inhibitors, and consistent with this SMARCA4-deficiency, has been shown to be a strong predictor of sensitivity to CDK4/6 inhibitors in NSCLC and SCCOHT tumor models." (PMID 38180245, 2024). "Immunohistochemically, the tumor cells were partially positive for cytokeratin (AE1/AE3), epithelial membrane antigen (EMA), cluster of differentiate 56 (CD56), synaptophysin, and CD10 and loss for SMARCA4, chromogranin A, and thyroid transcription factor-1 (TTF-1)." (PMID 38903333, 2024). "However, the functional significance of these SMARCA4 alterations in tumor development remains unknown." (PMID 37919824, 2023). "H358 tumours are resistant to IACS-10759 due to the absence of the SMARCA-4 mutation found in A549." (PMID 37679822, 2023). "Therefore, the upregulation of SMARCA4 in the OSCC tissues is positively correlated with tumor progression, suggesting that SMARCA4 may play an oncogenic role in OSCC." (PMID 36902184, 2023). "Histologically, SMARCA4-DTS is a poorly differentiated tumor with rhabdoid or epithelioid features that can be distinguished from other soft tissue, and thoracic sarcomas by a higher tumor mutation burden (TMB) and the presence of smoking signatures, including KRAS, STK11, and KEAP1 mutations." (PMID 37378131, 2023). "Ancillary testing for some specific tumours (e.g. SMARCA4-deficient (lung) adenocarcinoma–which is typically TTF-1 negative) is not available or not done routinely on brain metastatic specimens (e.g. lung biomarker panel); this limits the ability of the pathologist to classify some tumours." (PMID 37943775, 2023). "It has been hypothesized that the dual deficiency in key members of the SWI/SNF complex (e.g., SMARCA4 and SMARCA2, or SMARCB1 and SMARCA2) can induce dedifferentiation from a normal cell or a low-grade tumor into an aggressive high-grade tumor with small cell and/or rhabdoid features." (PMID 35200537, 2022). "In addition, we observed one tumor with complete absence of SMARCA4 expression (T19) which was associated with a truncation mutation (p.Val1171fs) in SMARCA4 and one additional tumor with focal loss in areas of dedifferentiation (T10)." (PMID 33435234, 2021).
tumor (continued). "In view of all these reported cases, there is a high possibility that ICI therapy can be considered as a treatment option for SMARCA4-deficient tumors with or without a PD-L1 IHC response by efficiently reducing tumor burden both clinically and symptomatically." (PMID 34440689, 2021). "Furthermore, these findings may also suggest that additional oncogenic signaling pathways, downstream of TGFβ, may be activated by the SOX4/SMARCA4 complex and contribute to tumor development and progression." (PMID 33837205, 2021). "Moreover, the role of SMARCA4 alterations in tumor diagnosis and treatment was also summarized." (PMID 33836796, 2021). "In addition, some tumours can now be identified by molecular genetic analysis, for example, NUT (NUclear protein in testis) carcinoma and SWI/SNF chromatin remodelling complex, particularly its subunits SMARCA4 (BRG1)- and SMARCB1 (INI-1)-deficient carcinomas." (PMID 34573868, 2021). "Whole‐genome sequencing and various new techniques to investigate 3D chromatin architecture may offer substantial insight into the full breadth of the effects resulting from SMARCA4 dysfunction, as well as other subunits, and reveal their diverse contributions towards oncogenesis and tumour biology." (PMID 32162380, 2020). "Although BRG1 expression is found to be upregulated in the vast majority of human HCC samples, it is worth to note that a small percentage of HCCs have low expression of BRG1 or harbor inactivating SMARCA4 mutations, suggesting a possible tumor suppressor role of BRG1." (PMID 32019910, 2020). "In contrast, instead of suggesting SMARCA4 as a tumour suppressor gene, Kaufmann et al45 provided evidence that the over‐expression of SMARCA4 was observed to enhance cell growth and invasiveness of HCC and that it might be linked to cyclin B, cyclin E and matrix metalloproteinase 7 (MMP7)." (PMID 32162380, 2020). "One tumor (IGR-03) diagnosed as SCCOHT did not exhibit a SMARCA4 mutation but instead, harbored concomitant and potentially biallelic loss-of-function alterations in two other SWI/SNF genes: ARID1A (two frameshifts—p.Q555fs and p.T1004fs) and ARID1B (stop gained R1944*)." (PMID 32575483, 2020). "Consequently, SMARCA4 (BRG1) protein expression in this tumor was retained by IHC." (PMID 32575483, 2020). "Taken together, our results demonstrated that the migration of ATRT cancer and tumor growth were mediated by the uptake of tMSC-derived exosomes containing abundant miR-155, which in turn led to a downregulated expression of endogenous SMARCA4 in recipient cells." (PMID 31137686, 2019). "In addition, several studies have shown that SMARCA4 is required for tumor cell proliferation." (PMID 29391527, 2018). "Using data on SMARCA4 mutations in 18 types of tumors obtained from TCGA through cBioPortal48, we found SMARCA4 to be mutated in either none or up to 8.5% of the samples, depending on the tumor type." (PMID 29391527, 2018). "Therefore, our data are not incompatible with a role of SMARCA4 as a tumor suppressor when it is mutated in certain types of tumors, probably due to the pathological activity of aberrant residual SWI/SNF complexes." (PMID 29391527, 2018).